KANSL3 (KAT8 regulatory NSL complex subunit 3)
Description:
Non-catalytic component of the NSL histone acetyltransferase complex, a multiprotein complex that mediates histone H4 acetylation at 'Lys-5'- and 'Lys-8' (H4K5ac and H4K8ac) at transcription start sites and promotes transcription initiation. The NSL complex also acts as a regulator of gene expression in mitochondria. Within the NSL complex, KANSL3 is required to promote KAT8 association with mitochondrial DNA. Required for transcription of intraciliary transport genes in both ciliated and non-ciliated cells (By similarity). This is necessary for cilium assembly in ciliated cells and for organization of the microtubule cytoskeleton in non-ciliated cells (By similarity). Also required within the NSL complex to maintain nuclear architecture stability by promoting KAT8-mediated acetylation of lamin LMNA (By similarity). Plays an essential role in spindle assembly during mitosis. Acts as a microtubule minus-end binding protein which stabilizes microtubules and promotes their assembly. Indispensable during early embryonic development where it is required for proper lineage specification and maintenance during peri-implantation development and is essential for implantation (By similarity).
Synonyms: KIAA1310; NSL3; FLJ10081; Rcd1
Tractability: PROTAC: ubiquitination databases record sites on it; its protein half-life has been measured.
Gene: Protein-coding gene on chromosome 2 (96,593,170 to 96,642,787, reverse strand). Ensembl gene ENSG00000114982.
Subcellular location: Nucleus; Mitochondrion; Cytoplasm, cytoskeleton, spindle pole
Subcellular location (Human Protein Atlas): Nucleoplasm; Vesicles
Pathways (Reactome):
Chromatin organization: HATs acetylate histones
Gene expression (Transcription): Formation of WDR5-containing histone-modifying complexes
Gene Ontology:
Molecular function: protein binding
Biological process: regulation of mitochondrial transcription; positive regulation of DNA-templated transcription; positive regulation of transcription by RNA polymerase II
Cellular component: histone acetyltransferase complex; mitochondrion; NSL complex; nucleoplasm; nucleus; spindle pole
Genetic constraint (gnomAD): Loss-of-function variants: 15 observed, 78.96 expected, observed/expected ratio (o/e) 0.19, 90% interval 0.13 to 0.29. The upper end of that interval is the gene's LOEUF score, 0.29, which puts it in group 1 of 6, group 1 being the genes least tolerant of losing a copy. Missense variants: 879 observed, 1,072.4 expected, observed/expected ratio (o/e) 0.82, 90% interval 0.77 to 0.87. Synonymous variants: 385 observed, 404.22 expected, observed/expected ratio (o/e) 0.95, 90% interval 0.88 to 1.04.
Homologues: Orthologues: chimpanzee KANSL3 (100% identical), macaque KANSL3 (99% identical), dog KANSL3 (97% identical), pig KANSL3 (97% identical), rabbit KANSL3 (95% identical), rat Kansl3 (95% identical), mouse Kansl3 (94% identical), guinea pig KANSL3 (93% identical), tropical clawed frog kansl3 (72% identical), zebrafish kansl3 (62% identical), Drosophila melanogaster Rcd1 (28% identical), Caenorhabditis elegans sumv-2 (19% identical). Paralogues in human: TEX30 (6% identical).
Diseases named in the same sentence as KANSL3 in open-access papers:
KANSL3 is named in the same sentence as 7 diseases in open-access papers, as found by Europe PMC text mining. Sharing a sentence is not in itself a finding about the gene and the disease. The quoted sentences say what the papers report.
Hepatic fibrosis (1 paper, 2025). The presence of excessive fibrous connective tissue in the liver. "We conclude that KANSL3 is an essential component of the NSL complex in liver tissue, and its loss in hepatocytes leads to liver dysfunction in 3-wk-old mice resulting in liver fibrosis and the development of a biliary hyperplasia (ductular reaction)." (PMID 41044006, 2025). "Hepatocyte-specific deletion of the epigenetic regulator KANSL3, a key component of the NSL complex, results in early-onset liver disease marked by biliary hyperplasia and hepatic fibrosis." (PMID 41044006, 2025).
liver disease (1 paper, 2025). "Taken together, our findings showed that KANSL3 loss in hepatic epithelial cells leads to severe liver disease in young mice." (PMID 41044006, 2025). "Remarkably, already in neonates Kansl3 LKO mice developed fibrosis, a ductular reaction, and serum analysis identified liver disease markers in Kansl3 LKO neonates compared with age-matched controls." (PMID 41044006, 2025). "We found that the deletion of KANSL3 in hepatocytes in vivo leads to early-onset liver disease, characterized by biliary hyperplasia and fibrosis." (PMID 41044006, 2025). "Hepatocyte-specific deletion of KANSL3 in neonatal mice leads to rapidly progressing liver disease, characterized by biliary hyperplasia and fibrosis, indicating defects earlier in development." (PMID 41044006, 2025). "Collectively, we demonstrated a crucial role of the epigenetic regulator KANSL3 in hepatocyte differentiation in liver development and disease, identifying it as a potential target for therapeutic intervention in the treatment of liver disease." (PMID 41044006, 2025). "Although developmental defects were ruled out in Ogt LKO mice, these animals develop liver disease and fibrosis by 4 wk of age with gene expression changes resembling those in 3-wk-old Kansl3 LKO mice." (PMID 41044006, 2025).
steatosis (1 paper, 2025). Increased lipid within the cytoplasm of cells. "Typical features of classical MASH progression, such as micro- and macrovesicular steatosis, were absent in Kansl3 LKO mice at P21." (PMID 41044006, 2025).
tumor (4 papers, 2022 to 2025). "Currently, more studies on the relationship between −TIPs and tumor prognosis have been conducted on CAMSAPs and ASPM, while fewer studies have been conducted on the relationship between γ-TuRC, KANSL3 and CEP170B and tumor prognosis, mainly focusing on gliomas." (PMID 41464116, 2025).
cancer (1 paper, 2023). A tumor composed of atypical neoplastic, often pleomorphic cells that invade other tissues. "KANSL3 and LSM11 are novel targets as not much is previously published about them in regards to cancer." (PMID 37161535, 2023).
KANSL3 also shares sentences with these, for which no sentence is quoted: fatty liver disease (1 paper); hepatocellular carcinoma (1).